BUB1B-PAK6 (BUB1B-PAK6 readthrough)
Gene: Protein-coding gene on chromosome 15 (40,218,500 to 40,264,890, forward strand). Ensembl gene ENSG00000259288.
Genetic constraint (gnomAD): Missense variants: 64 observed, 84.14 expected, observed/expected ratio (o/e) 0.76, 90% interval 0.62 to 0.94. Synonymous variants: 27 observed, 31.8 expected, observed/expected ratio (o/e) 0.85, 90% interval 0.62 to 1.17.